VASP (vasodilator stimulated phosphoprotein)
Diseases named in the same sentence as VASP in open-access papers (continued):
Sharing a sentence is not in itself a finding about the gene and the disease.
Macrothrombocytopenia (1 paper, 2021). "Taken together, our findings identify zyxin as a regulator of platelet biogenesis and GPIb-IX surface expression through VASP-mediated cytoskeleton reorganization, suggesting possible pathogenesis of macrothrombocytopenia." (PMID 34657146, 2021).
oral squamous cell carcinoma (1 paper, 2025). "VASP was found to be overexpressed in metastatic oral squamous cell carcinoma (OSCC) tissues." (PMID 39792809, 2025).
papillary adenocarcinoma (1 paper, 2008). A morphologic variant of adenocarcinoma. "High expression of VASP and formin-binding protein in the papillary adenocarcinoma triggers long unbranched filaments termed filopodia, which are frequently observed in cell-cell contacts." (PMID 18811984, 2008).
pneumonia (1 paper, 2014). An acute, acute and chronic, or chronic inflammation focally or diffusely affecting the lung parenchyma, caused by an infection in one or both of the lungs (by bacteria, viruses, fungi, or mycoplasma.). "The related research by Janek Henes's indicates that NF-κB activation accelerates the increase of alveolar-capillary permeability during TNF-α-induced pneumonia in VASP knockout mice." (PMID 25051011, 2014).
prostate tumour (1 paper, 2024). "Another study suggests that EGF receptor‐mediated prostate tumour progression is dependent on STAT3, which regulates the expression of VASP (motility‐limiting vasodilator‐stimulated phosphoprotein), and the apoptosis nexus CASP3." (PMID 39641316, 2024).
pulmonary stenosis (1 paper, 2020). "We also report novel plausible gene–disease associations for tetralogy of Fallot/pulmonary stenosis (CDC42BPA, FGD5), hypoplastic left or right heart (SMARCC1, TLN2, TRPM4, VASP), congenitally corrected transposition of the great arteries (UBXN10), and early-onset cardiomyopathy (TPCN1)." (PMID 32037394, 2020).
retinal degeneration (1 paper, 2021). Degeneration of the retina. "The peptide VASP_150_162 is one of the three VASP peptides that is phosphorylated by PKGs and frequently used as a read out for PKG activity in studies on retinal degeneration." (PMID 33503999, 2021).
Right ventricular hypertrophy (1 paper, 2016). In this case the right ventricle is more muscular than normal, causing a characteristic boot-shaped (coeur-en-sabot) appearance as seen on anterior- posterior chest x-rays. "Under both hypoxic conditions right ventricular hypertrophy was observed (p < 0.01) and endothelial NOS mRNA increased (p < 0.001), but the phosphorylated/nonphosphorylated vasodilator-stimulated phosphoprotein (VASP) ratio was unchanged." (PMID 27313889, 2016).
sleep-disordered breathing (1 paper, 2018). "Because of the poor correlation among drug concentrations, the VASP-PRI, and platelet aggregation in patients who have clopidogrel, the cAMP signalling pathway, other than P2Y12, may be modified by the presence of sleep-disordered breathing." (PMID 29568240, 2018).
subarachnoid hemorrhage (1 paper, 2021). A serious neurological disorder characterized by intracranial hemorrhage into the subarachnoid space. "Subarachnoid hemorrhage can reduce the expression of p-Vasp/Vasp in the basilar artery, while a metabotropic glutamate receptor 1 (mGLUR1) negative allosteric modulator can restore the expression of p-Vasp/VASP in the basilar artery after subarachnoid hemorrhage." (PMID 34630032, 2021).
thrombotic disorders (1 paper, 2023). "The regulations of VASP and integrin αIIbβ3 are critical for maintaining hemostasis and preventing thrombotic disorders because they play important roles in platelet function, including clot retraction." (PMID 37569361, 2023).
cancer (42 papers, 2012 to 2025). A tumor composed of atypical neoplastic, often pleomorphic cells that invade other tissues. "Vasodilator-stimulated phosphoprotein (VASP) is associated with the proliferation, invasion, and metastasis of malignant tumor cells." (PMID 40092702, 2025). "Note that ArpC5 expression and Ena/VASP expression are associated with increased metastasis and poorer overall survival in different cancers." (PMID 36662867, 2023). "More importantly, VASP plays a key role in the progression of several malignant tumors and is associated with malignant cell proliferation, invasion, and metastasis." (PMID 37962042, 2023). "In summary, VASP is closely linked to the occurrence and progression of malignant tumors." (PMID 37962042, 2023). "Another study, showed that VASP expression is increased in HSCs associated with liver metastasis both in experimental mice and cancer patient samples and this is required for TGFβ signalling, differentiation of normal HSCs to myofibroblasts and CAF paracrine function." (PMID 33573141, 2021). "Notably, VASP was reported to increase cell protrusion activities, and has been implicated in cancer invasion and migration." (PMID 29703977, 2018). "This suggests that signals from RBCs of metastatic patients lead to the accumulation of VASP at the leading edge of cancer cells, promoting directed migratory capabilities." (PMID 40301999, 2025). "According to the current model, the actin subunits provided by Cofilin 1-mediated actin cleavage are used by the Arp2/3 complex and by VASP to elongate F-actin at the tips of cellular protrusions and thereby drive migration and invasion of cancer cells." (PMID 39281318, 2024). "We have summarized the role of VASP in tumor development and progression according to the classification of malignant tumors." (PMID 37962042, 2023). "After cancer patients receive chemoradiotherapy, it is also worth exploring to evaluate the treatment effect by detecting the changes in VASP expression in the blood." (PMID 37962042, 2023). "In this review, we have summarized the fundamental features of VASP and its modulation in various malignant tumors." (PMID 37962042, 2023). "VASP is highly expressed in several malignant tumors; interacts with various molecules to promote cancer cell proliferation, migration, and invasion; and plays an important role as an oncogene during tumor development." (PMID 37962042, 2023). "Here, we have summarized current studies on the impact of VASP on the development of several malignant tumors and their mechanisms." (PMID 37962042, 2023). "Among the various downstream effectors of PKG, VASP regulation in cancer or cardiovascular diseases has been studied due to its role in cell adhesion, migration, and proliferation." (PMID 35883611, 2022). "Our work uncovers a conformational mechanism of interaction specificity that distinguishes highly similar paralogs and establishes tools for dissecting specific Ena/VASP functions in processes including cancer cell invasion." (PMID 34854809, 2021). "FAT3 was relatively less studied and was thought to participate in the development of human cancer through a pathway similar to that of the Ena/VASP proteins." (PMID 33816234, 2021). "Nevertheless, recruitment of CD4+ activated T cells to inflammatory sites is severely compromised in double Ena/VASP knockout mice due to defective transendothelial migration, suggesting a suppressing mechanism of cancer immunity." (PMID 33573141, 2021). "Post-translational modification of VASP by phosphorylation is an important regulatory mechanism in cell migration of fibroblasts and cancer cells." (PMID 34913099, 2021). "Overexpression of VASP promotes cancer cell invasion and metastasis and is positively associated with poor TNM stage and poor prognosis in several human cancers, including HCC 21, 36-38." (PMID 32206125, 2020).
cancer (continued). "In colon cancer cells phosphorylation of VASP at Ser 239 suppressed the formation of filopodia and invadopodia inhibiting the migration of cancer cells." (PMID 33171868, 2020). "Previous studies have demonstrated that Lpd promoted invasive 3D cancer cell migration via its interactions with Ena/VASP proteins." (PMID 30728082, 2019). "Together, our clinical data support that high VASP levels of GI cancer cells correlate with cancer metastasis and reduced patient survival." (PMID 29872721, 2018). "Matrine and berberine are two plant extracts from Chinese herbal medicine and they have been shown to bind to VASP to interfere its function so as to inhibit cancer cell proliferation and migration." (PMID 29872721, 2018). "Mechanistically, we show that Lamellipodin promotes invasive 3D cancer cell migration via both actin-elongating Ena/VASP proteins and the Scar/WAVE complex, which stimulates actin branching." (PMID 26996666, 2016). "Here, we report that Lamellipodin mediates invasive 3D migration of cancer cells via selective, regulated interactions with Ena/VASP and Scar/WAVE." (PMID 26996666, 2016). "VASP and MENA are reportedly associated with invasiveness, suggesting that IRSp53 signaling to VASP or possibly to the MENA pathway would be important for cancer cell metastasis in vivo." (PMID 23555988, 2013). "In addition, VASP can modify the activation of signaling pathways involved in cell growth and proliferation, making it a promising target for cancer therapy." (PMID 37962042, 2023). "The miR-1-3p-mediated inhibition of VASP could serve as a potential mechanism to suppress cancer progression and enhance the chemotherapy sensitivity of BC cells." (PMID 35813865, 2022). "In lung cancer, the differential expression of VASP between normal and cancer tissues suggests that it may regulate the invasive behavior of cancer cells." (PMID 33171868, 2020). "YC-1 induced VASP phosphorylation at Ser157 and Ser239 under both normoxic and hypoxic conditions, indicating that YC-1 was able to activate cGMP-dependent and/or cAMP-dependent pathways in A549 cancer cells." (PMID 30634531, 2019). "Thus, targeting VASP of cancer cells significantly suppressed liver metastatic growth in both male and female mice." (PMID 29872721, 2018). "In summary, VASP is a therapeutic target for liver metastasis of GI cancers and our future studies need to focus on novel approaches by which we can screen, identify, and develop compounds to target VASP of both cancer cells and stromal cells." (PMID 29872721, 2018). "What’s more, they showed that knocking down VASP of cancer cells in metastasis mouse models suppressed cancer metastatic growth in the liver, suggesting that the same might be true in patients as well." (PMID 29872721, 2018). "While Ena/VASP proteins can be upregulated in some human cancers and their expression may be increasing with progression of the disease, the exact functional consequences of expression changes of Ena/VASP proteins to cancer cell biology remain elusive." (PMID 23166783, 2012). "Targeting VASP using drugs may prevent cells from becoming cancerous, or slow the spread of cancer." (PMID 37962042, 2023). "Thus, the coordination of Arp2/3 and VASP may regulate the plasticity of protrusion phenotypes, and the functional deregulation of VASP or its isoforms in cancer may promote cellular migratory behaviors by promoting accelerating protrusion." (PMID 29703977, 2018). "Thus, VASP is required for the growth of 3D cancer spheroids on ECM." (PMID 29872721, 2018). "Thus, VASP of cancer cells represents as a therapeutic target for metastatic CRCs and PDACs." (PMID 29872721, 2018). "Elevated EMP1 inhibits the interference of SMAD7 with SMAD2/3 activity by promoting the binding of VASP to SMAD7, ultimately activating the TGF-β/Smads signaling pathway-induced cancer cell invasiveness." (PMID 41285728, 2025).
cancer (continued). "Other GDTLs we detected like CXCR1, VASP, ZYX, GPR137 and GOLPH3 were reported as known markers in many cancers." (PMID 33179221, 2021). "Considering the important role of PDPK1 20 and VASP 21 in cancer invasion and metastasis, we focused on PDPK1 and VASP for further study." (PMID 32206125, 2020). "In agreement with these, preclinical studies with two experimental liver metastasis mouse models demonstrate that VASP knockdown suppresses GI cancer liver metastasis, β1-integrin activation, and YAP1/TAZ levels of metastatic cancer cells." (PMID 29872721, 2018). "Here, we report that vasodilator-stimulated phosphoprotein (VASP), an actin binding protein, is required for ECM–mediated β1-integrin-FAK-YAP1/TAZ signaling in gastrointestinal (GI) cancer cells and their liver metastasis." (PMID 29872721, 2018). "Solid Tumors: Using the cervical HeLa cancer cell line, cranberry proanthocyanidin extract (CPAC, from Vaccinium macrocarpon, up to 100 μg/mL, 4 h) disrupted actin polymerization along with delocalization of VASP to focal adhesions and α-actinin/paxillin." (PMID 36355554, 2022). "Moreover, vasodilator-stimulated phosphoprotein (VASP) and VEGF expressions were decreased in cancer cells in the B16 murine tumors co-treated with resveratrol and 5-FU." (PMID 30791624, 2019). "We determined that this is cancer cell specific since addition of Nisch to Cos7 cells does not affect VASP expression." (PMID 29415725, 2018). "Intriguingly, the role of Ena/VASP proteins in cancer progression and/or prognosis is not the same for all family members." (PMID 26221026, 2015). "In contrast to Mena and EVL-1, VASP expression levels do not serve as good predictive tumor markers, since they are generally high in both normal tissue and cancer." (PMID 26336132, 2015). "We currently do not know how VASP promotes β1-integrin activation in cancer cells." (PMID 29872721, 2018). "Although these data cannot tell us precisely whether VASP modulates YAP1/TAZ at downstream or upstream of RhoA, the data are of clinical significance given the high relevance of the GPCR-RhoA-YAP1/TAZ signaling cascade in cancer progression and metastasis." (PMID 29872721, 2018). "However, the exact link between VASP and cancer is still not entirely clear." (PMID 36294546, 2022).
tumor (39 papers, 2012 to 2026). "Interestingly, overexpression of these targets, such as matrix metalloproteinase-9, ras homolog family member A and vasodilator-stimulated phosphoprotein, have been demonstrated to be associated with tumor migration and invasion." (PMID 27474169, 2016). "PTTG1 and VASP knockdown noticeably reduced the metastatic cell adhesion of tumor cells to the lungs after tail vein injection by treatment with siRNA‐PTTG1 or siRNA‐VASP, compared with the control." (PMID 39792809, 2025). "These mouse models indicate that the depletion of PTTG1 and VASP represses metastatic tumor cell adhesion of OSCC in vivo." (PMID 39792809, 2025). "While LUM (lumican), DCN (decorin) and VASP (vasodilator stimulated phosphoprotein), that are known tumor suppressors were found to be downregulated in the EVs derived from NB patients." (PMID 38660306, 2024). "As an important cytoskeletal regulatory protein, VASP, induced by lysophosphatidic acid, regulates tumor cell migration by affecting lamellipodia formation." (PMID 37962042, 2023). "Clinically, we can perform IHC on patients' tumor tissues to detect the staining intensity of VASP to guide the appropriate treatment plan and predict survival." (PMID 37962042, 2023). "In this review, we have also consulted the literature on the role of VASP-HIF-1α interactions in regulating tumor development." (PMID 37962042, 2023). "High expression of VASP cloud be combined with some classic tumor markers (such as prostate-specific antigen, carcinoembryonic antigen, alpha-fetoprotein, etc.) to evaluate the prognosis of patients." (PMID 37962042, 2023). "There are many evident and promising directions for the study of VASP in future tumor research; however, VASP is involved in too many tumors and mechanisms." (PMID 37962042, 2023). "In vivo assay further validated the tumor-promoting effect of Exo-MALAT1 via regulation of the miR-1-3p/VASP/Rap1 axis." (PMID 35813865, 2022). "The overexpression of both PDPK1 and VASP was positively correlated with maximal tumor size and higher TNM stage." (PMID 32206125, 2020). "VASP is an actin‐related skeletal protein that plays an important role in regulating tumor cell migration and invasion." (PMID 30806044, 2019). "It was found that knockdown of VASP can significantly slow down the growth rate of the tumor and ultimately reduce the weight and volume of the tumor." (PMID 31754343, 2019). "For WB, five liver metastases were recovered from control and three were recoved from VASP knockdown group due to small tumor sizes in this group." (PMID 29872721, 2018). "The possible mode of action includes effects on vasodilator-stimulated phosphoprotein (VASP) which is reported to be crucial in cell migration as well tumor metastasis." (PMID 27445824, 2016). "Some attempts have been made to link phosphorylation of VASP at certain residues to tumor survival or progression." (PMID 26336132, 2015). "Additionally, a risk score (RS) for predicting tumour relapse after NAC and cystectomy was calculated for each patient according to a mathematical algorithm containing FN1, VASP, and CEP63." (PMID 40149716, 2025). "Recent studies have reported a close relationship between VASP expression and tumor progression." (PMID 39792809, 2025). "Mechanistically, these findings were linked to the downregulation of tumor-promoting molecules, including cyclooxygenase-2 (COX-2), vascular endothelial growth factor [VEGF], and vasodilator-stimulated phosphoprotein (VASP), alongside an upregulation of AMP-activated protein kinase (AMPK)." (PMID 41463545, 2025). "VASP overexpression contributes to increased tumor growth and progression." (PMID 37962042, 2023). "This suggests that VASP enhances tumor invasion and metastasis by promoting tumor cell migration." (PMID 37962042, 2023). "Surprisingly, VASP overexpression also led to NIH 3T3 tumor formation, suggesting that normal cell growth may require the control of VASP protein expression within appropriate limits." (PMID 37962042, 2023).